MET (MET proto-oncogene, receptor tyrosine kinase)
Diseases named in the same sentence as MET in open-access papers (continued):
Sharing a sentence is not in itself a finding about the gene and the disease.
tumor (continued). "Dysregulation of the MET/HGF pathway leads to uncontrolled cell proliferation and oncogenesis and is observed in multiple tumour types." (PMID 33526881, 2021). "Having found changes in tumor uptake of 89Zr-radiolabeled antibodies after treatment with cetuximab or with INC280 and trametinib, we next investigated changes in MET, EGFR, and HER2 protein levels at the cellular level." (PMID 32646879, 2021). "Co-administration of c-MET inhibitors and TMZ demonstrated favorable drug synergism that significantly attenuated GPC tumor xenografts' growth." (PMID 33859738, 2021). "For example, as a tumor inhibitor, CYP1A2 suppressed tumorigenicity by inhibiting HGF/MET and reduced the sensitivity of sorafenib via inhibiting the NF-kB signaling." (PMID 34900444, 2021). "Metastasis Associated in Colon Cancer-1 (MACC1) has been shown to modulate tumor cell growth and activate invasion and metastasis, mainly by activation of the HGF/MET oncogenic pathway." (PMID 33731131, 2021). "Three of the type 1 pRCC cell line models (UOK208, UOK337, and UOK345) demonstrated activating mutations of the MET gene, including the first cell line ever derived from a tumor excised from an HPRC patient (UOK345), and all cell lines demonstrated MET gain." (PMID 33527590, 2021). "Certain kinases, notably PI3K/Akt, Src, c-MET, VEGFR1/2/3, and FLT3 were over-represented by multiple inhibitors, implying that these targets are likely to be true positives and key mediators of tumor hypoxic adaptation." (PMID 33859738, 2021). "We found that c-MET and EGFR expression levels were independent biomarkers for clinical prognosis, and their high expressions were correlated with tumor progression and a poor prognosis of CRC." (PMID 34512327, 2021). "First, the biological functions of MET, OAS1, and OASL such as their interactions with immune cells in tumor microenvironment need to be explored in vitro experiments." (PMID 33869254, 2021). "We also addressed if c-MET and ILEI had a consequence on tumor vascularization by determining blood vessel density and size on CD31 immunostained tumor sections." (PMID 33596971, 2021). "On the other hand, many DEGs related to tumor development, such as hepatocyte growth factor (HGF) and hepatocyte growth factor receptor (MET), were downregulated." (PMID 33732214, 2021). "Previous researches showed that as a transcription factor, the downstream of ETS1 were several classic tumor-related genes, such as RAS, MET, ERK and etc." (PMID 33999777, 2021). "Conversely, as also observed in patients, the crizotinib (anti-MET TKI) and osimertinib combination improved survival and reduced tumor burden in EGFR/MET mice, further validating the model’s value for preclinical studies." (PMID 34298655, 2021). "MET inhibitor cabozantinib (also inhibits VEGFR2, AXL, KIT, RET) has been studied as an inhibitor of angiogenesis and tumor growth in many tumor diseases." (PMID 34212564, 2021). "The proto‐oncogene mesenchymal–epithelial transition (MET) tyrosine kinase and its ligand hepatocyte growth factor (HGF) play an important role in the migration, proliferation, and invasion of tumour cells." (PMID 34761497, 2021). "We demonstrated that disrupting this tumor-CAF communication loop by capmatinib and osimertinib combination regimen (suppressing MET/Akt/EGFR) overcame osimertinib resistance." (PMID 33621951, 2021). "Collectively, our data suggested that DNM3 suppresses LC tumor growth and migration by interacting with GBR2, which subsequently leads to the dissociation of the c-MET and STAT3 complex." (PMID 34490234, 2021). "Phosphorylation of MET induces the activation of PI3K/AKT and RAS/RAF/MAPK cascades to rescue tumour cells from EGFR inhibitors." (PMID 34663410, 2021).
tumor (continued). "Also some novel biomarkers were investigated to predict the survival outcome of PSC, such as CD8+ tumor-infiltrating lymphocytes, the epithelial−mesenchymal transition transcription factors (Twist1), the change of neutrophil-to-lymphocyte ratio, KRAS mutations and c-MET overexpression." (PMID 34136380, 2021). "Compared with anti EGFR mAb or anti c-MET mAb alone, EMB-01 induces significantly stronger anti-tumor activity in PDX and CDX tumor models." (PMID 34025638, 2021). "Foretinib acts by inhibiting HGF-induced MET phosphorylation, VEGF-induced phosphorylation and precludes both HGF-mediated responses of tumor cells and HGF/VEGF-stimulation." (PMID 33918490, 2021). "Repurposed c-MET inhibitors PF04217903 and tivantinib exhibited hypoxic-dependent drug synergism with temozolomide, resulting in reduced tumor load and growth of GPC xenografts." (PMID 33859738, 2021). "This disruptive effect was mostly abrogated with inhibitors of MMP or hepatocyte growth factor (HGF) receptor (c-MET), in accordance with other studies reporting the contribution of CAF-derived mediators to tumour progression." (PMID 34572836, 2021). "Resistance is typically associated with amplification of MET or FGFR1, supporting the ability of MET and FGFR to activate similar key signalling pathways required for tumour progression." (PMID 33772015, 2021). "Conversely, the higher rate of co-occurrent alterations, either “passengers” or even “drivers”, in MET, KRAS, BRAF and EGFR-driven tumors, suggests a branched clonal evolutionary process existing from the early steps of tumor progression." (PMID 33946519, 2021). "The three novel MET, FGFR4, and ERBB3 isoforms were predicted to be initiated from promoters distinct from their annotated TSSs (51 kb away (MET), 438 bp (FGFR4), 248 bp (ERBB3), and upregulated in tumor samples to a greater degree from their known isoforms." (PMID 33482911, 2021). "We found it difficult to distinguish between tumor samples and normal samples when using HGF, c-MET, or immune infiltration scores alone." (PMID 34261467, 2021). "Alternatively, injection of the v6 peptides that block the co-receptor functions of CD44v6 for MET and VEGFR-2 inhibited human pancreatic xenograft tumor growth and metastasis and decreased survival of KPC mice." (PMID 34349642, 2021). "At 21 days, significant tumor inhibition was observed in NF1-MET tumors and in the surviving cells, the kinome adaptations observed with single MET inhibition were intensified." (PMID 32245042, 2020). "We particularly found that this agent, which readily crosses the BBB, can significantly decrease tumor volumes, ADC values, MVD, and HNA, c-MET and ACVR1 protein expressions, compared to untreated tumors, as well as significantly increase apoptosis." (PMID 33168005, 2020). "Simultaneous blockade of VEGFA and ARP2/3, VEGFA and c-MET or VEGFA and ZEB2 suppresses tumor invasion." (PMID 32775327, 2020). "Study of the c-Met-HGF axis in non-small cell lung cancer (NSCLC) has focused on the roles of c-MET signaling in neoplastic epithelial cells and the secretion of its ligand hepatocyte growth factor (HGF) by tumor stromal cells." (PMID 32117721, 2020). "For example, miR-34c suppressed tumor growth and metastasis in NPC by targeting MET proto-oncogene (MET)." (PMID 32013999, 2020). "DYNLL1-related cytoskeletal rearrangement and tumor cell migration can be theoretically inhibited by anti-HGF therapy, as DYNLL1 shows indirect interaction with HGF in HGF/c-MET pathway in HNSCC." (PMID 32564264, 2020).
tumor (continued). "It has been reported that CD44−/CD24+ and ALDH1+ tumor cells represent two distinct tumor cell populations not only localized in different regions of the primary tumor tissue but also expressing distinct EMT and MET gene profiles." (PMID 32667137, 2020). "The main IPA analyses predicted outcomes due to combined downregulation of c-MET and PTGS2 by OC treatment in NSCLC include the suppression of tumor cell proliferation, migration and metastasis and induction of tumor cell death." (PMID 32545325, 2020). "Previously, we compared combined MET and MEK inhibition with monotherapy and demonstrated significant improvement in tumor inhibition and response variability with combination therapy compared to a single agent alone." (PMID 32245042, 2020). "As the upregulated ERBB1 and c-MET pathways contribute to BC progression and distant metastasis, we investigated the ability of NER and CBZ to prevent primary tumor growth and metastasis in the orthotopic model of spontaneous metastasis (n = 5)." (PMID 33019652, 2020). "Although the EGFR and CCND1 (cyclin D1) loci were triploid, and the MET locus was triploid with LOH, the transcriptome analysis showed only MET RNA overexpression in this tumor, contrasting with the findings from F8." (PMID 31963394, 2020). "Kwak et al3 reported patient cases of MET and ERBB2 coamplification occurring in the same tumor cells, including a single case of MET, ERBB2, and EGFR coamplification all occurring within a single tumor cell population." (PMID 32338752, 2020). "The levels of eight hub genes expression (FN1, CCND1, CDH2, CXCL12, MET, IRS1, DCN and FMOD) in PTC and para-cancerous non-tumor tissues were detected by qRT-PCR." (PMID 32714651, 2020). "The EMT process includes adherence junction components (e.g., E-cadherin (ECAD)), matrix metalloproteinase (MMP) 7 and 9, tumor microenvironment components (e.g., cyclooxygenase-2 (COX-2)), and c-MET." (PMID 32825724, 2020). "It is highly selective to MET and has a high inhibition potency, being up to 30 times more potent than Crizotinib, and recedes the EGFR TKI resistance in tumor cells." (PMID 33153004, 2020). "Especially, the candidates ABCA1, MET, and SCD were entangled with tumor metabolism, while FCGR1A and ITGB2 showed the widest interactions with immunological processes." (PMID 32228647, 2020). "A previous study has attempted to explain that lncRNA-MIR22HG played a tumor suppressive role through dysregulation of the oncogenes YBX1, MET, and p21, which resulted in reduced cell survival and increased cell death signaling in human primary lung tumors." (PMID 32219093, 2020). "The c-MET inhibitors crizotinib, foretinib, BMS-777607 and tivantinib all also enhanced basal levels of tumor cell death and enhanced [602 + doxorubicin] lethality." (PMID 32983965, 2020). "These genes were distributed in multiple pathways, and some of them, such as MET (ranked 1st), PRKDC (ranked 8th), EXO1 (ranked 14th), and TM4SF1 (ranked 25th), have been reported to promote tumor cell proliferation." (PMID 32995120, 2020). "The anti-tumor efficacy of LCD was shown through the dual inhibition of EGFR and MET activity, suggesting that it was a principal target of LCD." (PMID 32070026, 2020). "MET and AXL activate common downstream signaling pathways, including PI3K/AKT and MAPK/ ERK networks, leading to tumor growth, metastasis, drug resistance, immune suppression, and the stem cell phenotype." (PMID 34766112, 2020). "In fact, in AGS xenograft tumour models, co‐inhibition of PARP and c‐MET significantly reduced tumour growth compared to control or inhibitor alone." (PMID 32686903, 2020).
tumor (continued). "However, the EGFR T790M mutation, acquired RTK MET gene amplification and PIK3CA mutations, share the same effect of reestablishing the downstream PI3K/AKT/mTOR pathway in the presence of the anti-EGFR inhibitors, ultimately converting a TKI-sensitive tumor into a TKI-resistant tumor." (PMID 33123479, 2020). "The proto-oncogene MET, the hepatocyte growth factor (HGF) receptor, is a transmembrane receptor tyrosine kinase (RTK) with a prominent role in tumor metastasis and resistance to anti-cancer therapies." (PMID 32659961, 2020). "Their low levels in orthotopic tumors indicated that transplanted CXCR4+MET+CD44+ cells differentiated and lost marker expression during tumor formation." (PMID 32066735, 2020). "Further, the co-amplification and cross-talk between c-MET and ERBB1 pathways have been reported in different malignancies, including BC that regulates tumor progression, distant metastasis, and therapeutic resistance." (PMID 33019652, 2020). "MiR-199a-3p has been demonstrated to attenuate some oncogenes and antiapoptotic genes (i.e., MET, mTOR, MCL-1 and Bcl-XL, Stat3), suggesting its potential tumor suppressive role." (PMID 32565738, 2020). "In PNETs, tumor hypermethylation and silencing of long noncoding MEG3, determined activation of miR183/BRI3 axis, and cell proliferation due to c-MET oncogene activation." (PMID 33384663, 2020). "In tumor tissues, ABN401 was retained and inhibited c-MET phosphorylation from 0 to 12 h at doses of 10 and 30 mg/kg." (PMID 32549194, 2020). "We also found clonal indels in NF2 in two tumors (cdRCC and mixRCC), and MET (mixRCC), SMARCB1 (pRCC1) and ROS1 (pRCC2) indels in one tumor each." (PMID 32555180, 2020). "Thus, beneficial anti-tumor effects may be produced by inhibiting the MET signaling pathway." (PMID 33031392, 2020). "Preclinical and translational studies have indicated that activation of MET and PI3K signaling are important in tumor initiation and maintenance." (PMID 31776899, 2020). "Based on panel sequencing results with amplification of MET and KIT and tumor board decision, cabozantinib was initiated in a dose of 100 mg daily in the third relapse of the disease." (PMID 32758285, 2020). "We aimed to explore the tumor expression of HGF, c-MET, CXCL12, and CXCR4 and their correlation with patient overall survival (OS)." (PMID 32188473, 2020). "We investigated all patients for fusions with FGFR, neurotrophin tyrosine receptor kinase (NTRK), and MET and identified NTRK2 in one patient with a MGMT‐methylated tumor and FGFR3‐TACC3 in 3 patients (2.8%) all of which were in MGMT‐unmethylated tumors." (PMID 32885540, 2020). "One such RTK possibly involved in the DDR is MET, the RTK for hepatocyte growth factor (HGF) which is deregulated in abundance and/or activity in a variety of human tumor types and serves as an oncogenic target." (PMID 32336009, 2020). "Pioneer MET inhibitors such as SU11274, PHA665752, or AM7 were helpful for demonstrating the efficacy of MET inhibition to impair tumor growth in preclinical models." (PMID 32093126, 2020). "LY2801653 also inhibited the growth of MET and AXL‐independent cells at higher but clinically relevant doses through decreased angiogenesis and M2 macrophages in the tumor microenvironment." (PMID 34766112, 2020). "They revealed that XIST acts as a ceRNA for miR-34a via sponging miR-34a, competing with hepatocyte growth factor receptor (MET) for miR-34a binding, and decreasing ATC cell lines proliferation in vitro and tumor growth in vivo." (PMID 32760219, 2020).
tumor (continued). "To determine if MET status influences tumor response to HER2 inhibition, we examined the colony formation and tumor growth of isogenic H2170 clones treated with the HER2 TKIs (lapatinib, ASLAN001) and monoclonal antibodies (trastuzumab and pertuzumab)." (PMID 32214092, 2020). "The level of ctDNA (MET amplification and KRAS mutants) correlated with tumor burden and response to therapy." (PMID 31824558, 2019). "HGF induced activation of MET also triggers AKT or STAT3, induces epithelial–mesenchymal transition (EMT), and promotes multiple pro-tumor effects." (PMID 31367190, 2019). "However, because PD-L1 expression is regulated by cancer-cell-intrinsic (i.e., PD-L1 gene status and driver oncogenic pathways) and extrinsic (i.e., cytokine milieu) factors, the role of MET in PD-L1 induction might differ according to the tumor type and the tumor microenvironment." (PMID 31480591, 2019). "For EGFR, ERBB2, and MET gene amplification, we set the absolute copy number ≥6 as amplification for WES with tumor and normal pairs and log2 ratio ≥ 3-fold standard derivation (SD) as amplification for the ctDNA compared with a panel of normals." (PMID 31739500, 2019). "To confirm and validate these and other findings on the proteome level we performed immunohistochemical analyses for EGFR, MET, CA12 and AR on a number of tumours with low or high FPM values for the corresponding genes." (PMID 31747973, 2019). "Combined inhibition of MET/FAK and CDK4/6 eliminates the proliferation capacity of cancer cells in culture, and enhances tumour growth inhibition in vivo." (PMID 31296956, 2019). "It should be noted that copy gains of EGFR, FGFR1, MET, and ERBB2 have already been reported to be predictive markers for certain tumor types." (PMID 31480645, 2019). "Our data demonstrates that the combination of lapatinib plus foretinib did inhibit tumor progression in an OE33 experimental EAC model with co-activation of HER2 and MET." (PMID 31772236, 2019). "All tumors were analyzed using an NGS multi-gene panel that expands the tumor genetic portrait, including genes such as BRAF, ERBB2, KRAS, and MET in addition to EGFR and ALK/ROS1, in accordance with recently updated recommendations." (PMID 30669267, 2019). "A robust pipeline of high-quality inhibitors targeting different aspects of c-MET activation is currently being investigated in phase I, II, and III clinical trials across multiple tumor types." (PMID 30850583, 2019). "TAMs and CAFs have also been reported to be involved in tumor progression as well as in the RAS, MAPK, and MET signaling cascades." (PMID 31569444, 2019). "Immunosuppressive nature of hypoxia in PDAC microenvironment contributes to tumor survival in many aspects, such as promoting EMT progress through pathways including NOTCH and c-MET." (PMID 31139022, 2019). "Overall, our study demonstrates that combined PD901/MLN0128 treatment strongly inhibits tumor cell proliferation, leading to stable disease in AKT/c-MET HCC mice." (PMID 31277283, 2019). "In one osimertinib-resistant tumor, MET was found amplified by FISH analysis and a higher expression level of MET was also confirmed by western blot analysis, suggesting MET amplification as a potential mechanism of resistance to osimertinib." (PMID 31138260, 2019). "Foretinib is a small-molecule kinase inhibitor that inhibits cellular hepatocyte growth factor (HGF)-induced c-MET phosphorylation and prevents HGF-induced response to tumor cells." (PMID 31772236, 2019). "MET fusion was only detected in 4.8% (3/62) and 5.9% (1/17) of HCC tissues and adjacent non‐tumor tissues, respectively." (PMID 30903738, 2019). "MET gene copy-number gains were detected in the ctDNA of 2 of 16 patients, and FISH analysis of the paired tumor samples confirmed these results." (PMID 31320709, 2019). "The mRNA expression levels of COL17A1, CEP55, KLK10, MET, ITGB6, ANKRD22, and ARNTL2 were significantly increased in PAAD tumor tissue." (PMID 31612115, 2019).